FOXD3 (forkhead box D3)
Diseases named in the same sentence as FOXD3 in open-access papers (continued):
Sharing a sentence is not in itself a finding about the gene and the disease.
oesophageal cancer (1 paper, 2023). "The transcription factor forkhead box D3 (FOXD3) can bind directly to the promoter region of the SMAD7 gene, leading to the transcriptional promotion of SMAD7 in human oesophageal cancer cells, inhibition of the TGF-β pathway, and suppressive effects in oesophageal squamous cell carcinoma." (PMID 37685308, 2023).
oral cancer (1 paper, 2020). "Robustly, FOXD1, but not FOXD2, FOXD3 and FOXD4, was significantly (p < 0.01) upregulated in primary tumors compared to normal adjacent tissues derived from oral cancer patients deposited in the GSE42743 dataset." (PMID 32967107, 2020).
renal cell carcinoma (1 paper, 2013). "In contrast, knockdown of FOXD3 decreased the in vitro growth and invasion capabilities of renal cell carcinoma 786-O cells, without changes in the NDRG1 expression." (PMID 24269992, 2013).
thyroid (1 paper, 2023). "EMT regulatory networks in thyroid malignancy consist of transcriptional control by the TFs, for example, ZEB, SNAIL, TWIST, SOX9, Runx2, Forkhead box D3 (FOXD3), and epigenetic mechanisms, such as microRNA, DNA methylation, and lncRNA functions." (PMID 37046817, 2023).
ulcerative colitis (1 paper, 2021). An inflammatory bowel disease involving the mucosal surface of the large intestine and rectum. "In the FFPE (formalin-fixed paraffin-embedded) sections prepared from the colons of ulcerative colitis (UC) and immune-mediated colitis (IRAEC) patients, expression of DCLK1 isoforms correlated positively with Notch1 and negatively with a transcriptional repressor, FoxD3 (Forkhead Box D3)." (PMID 34226497, 2021).
tumor (41 papers, 2013 to 2025). "FOXD3, a member of the forkhead box family, has been suggested to be a tumor-associated transcription factor." (PMID 35273176, 2022). "Our study extends our knowledge on the underlying mechanism of the tumor suppressing function of FOXD3 by showing that FOXD3 also suppresses NPC by regulating miR‐26b." (PMID 28203521, 2016). "Furthermore, reduced FOXD3 protein expression in the knockdown tumor samples was also associated with low E-cadherin and high p-ERK1/2 levels compared with the controls." (PMID 28430585, 2017). "FOXD3 is important for maintaining epithelial cell identity, and its downregulation may contribute to the loss of epithelial characteristics, promoting a more invasive tumor phenotype." (PMID 41411347, 2025). "The Q-PCR analysis revealed that, as compared to those in control (Black) and negative control (Si-NC) cells, the mRNA expression levels of FOXD3 decreased in these tumor cells in the Si-FOXD3 group." (PMID 37151068, 2023). "HE staining analysis indicated obvious necrosis and inflammatory cell infiltration in tumor tissues of mice upon combined treatment with oe-FOXD3 and CP." (PMID 36627652, 2023). "FOXD3 mRNA and protein expression and miR-335 expression were upregulated while DAAM1 mRNA and protein expression along with extent of MLC2 phosphorylation was reduced in tumor tissues of mice co-treated with oe-FOXD3 and CP." (PMID 36627652, 2023). "In the present study, the database search showed that the FOXD3 gene was differentially expressed in various tumor tissues." (PMID 37151068, 2023). "Meanwhile, the positive pMLC2 expression was decreased in tumor tissues of CP-treated mice following overexpression of FOXD3." (PMID 36627652, 2023). "Real-time PCR analysis showed that the FOXD3 expression level of tumor was significantly higher than that in normal tissues." (PMID 30858761, 2019). "What’s more, FOXD3 plays a significant role in tumor initiation and growth through other transcription factors like TWIST1." (PMID 30858761, 2019). "According to Illumina450 genome-wide methylation data, FOXD3 methylation in tumor tissues was higher compared to paired normal tissues." (PMID 30858761, 2019). "We also found that FOXD3 was hypermethylated in tumor tissues compared to normal tissues in the top 20 candidate genes analyzed." (PMID 30858761, 2019). "FOXD3 can be considered a tumor suppressor since it inhibits tumor growth and angiogenesis of NSCLC and neuroblastoma, whereas its deficiency leads to the induction of EMT and increased invasiveness of breast cancer." (PMID 30360388, 2018). "For example, Nhlh1, which encodes a helix-loop-helix protein, was up-regulated in the Smo-OE group, and Foxd3, a tumor suppressor (Schmid and Müller, 2013), was down-regulated in the Smo-OE group." (PMID 29311816, 2017). "Consistent with MTT results, knockdown of FOXD3 significantly increased cell proliferation compared with the controls, indicating a tumor suppressor potential for FOXD3." (PMID 27926503, 2017). "We also observed that the levels of EGFR, K-Ras and p-ERK1/2 were markedly increased in mouse tumor injected with FOXD3-knockdown HCT116 cells compared with the controls." (PMID 27926503, 2017). "As expected, FOXD3 expression was significantly reduced in the tumor tissues compared with the normal tissues." (PMID 27926503, 2017). "This was further reflected by concomitant increase in tumor weight from FOXD3 knockdown SW1736 cells compared to controls." (PMID 28430585, 2017). "Western blot analysis from those tumor samples verified that FOXD3 protein expression was reduced in the knockdown tumor samples compared with the controls." (PMID 27926503, 2017). "FOXD3 is also a novel tumor suppressor that affects growth, invasion, metastasis and angiogenesis of neuroblastoma." (PMID 27926503, 2017).
tumor (continued). "In hepatocellular carcinoma, FOXD3 directly binds to the promoter of miR-137 and activates its transcription, while miR-137 exerted its anti-tumor activity via inhibiting the AKT2/mTOR pathway." (PMID 27926503, 2017). "FOXD3 is an important tumor suppressor that suppresses the growth, invasion, and metastasis of cancer cells." (PMID 26898989, 2016). "Many factors were predicted using 3 databases, and FoxD3 was selected for further validation due to its nature of a tumour suppressor." (PMID 24970808, 2014). "Compared with the control group, stable QGY-7703 and SK-Hep1 cells expressing miR-137 or FoxD3 generated tumours of lighter weight and smaller volume." (PMID 24970808, 2014). "We next investigated the efficacy of FOXD3 over-expression against tumor growth, metastasis and angiogenesis in vivo." (PMID 24269992, 2013). "Our results indicate that FOXD3 exhibits tumor suppressive activity that affects the growth, aggressiveness and angiogenesis of NB through transcriptional regulation of NDRG1." (PMID 24269992, 2013). "The tumor suppressor role of FOXD3 in GC was later identified, and its direct transcriptional targets CYFIP2 and RARB may act as a conduit for this role." (PMID 37215092, 2023). "FOXD3 could act as a tumor suppressor to impair cell viability and colony formation of OC A2780 cells." (PMID 36627652, 2023). "FOXD3 gene acts as a tumor suppressor gene in different kinds of tumors." (PMID 37151068, 2023). "Meanwhile, overexpression of FOXD3 reduced tumor volume and weight of CP-treated mice." (PMID 36627652, 2023). "In human GC, FOXD3 prevents the tumor cascade from being downregulated." (PMID 37215092, 2023). "FOXD3 is poorly expressed in OC tissues while its overexpression weakens OC cell proliferating and migrating ability and increases cell apoptosis while restraining tumor growth in vivo." (PMID 36627652, 2023). "In GC, FOXD3 is a tumor suppressor that has been epigenetically silenced." (PMID 37215092, 2023). "Aspirin can induce the up-regulation of forkhead box D3 (FOXD3) gene expression in tumor cells." (PMID 35505438, 2022). "Similarly, 5-Aza-dC was used as an epigenetic therapy and FOXD3 overexpression groups used as validation groups, the xenograft experiments revealed an obvious decrease of tumor weight and tumor volume in 5-Aza-dC group and FOXD3 overexpression groups." (PMID 30858761, 2019). "In vivo experiment detected that demethylated FOXD3 restrained tumor growth." (PMID 30858761, 2019). "It is reported that FOXD3 serves as a tumor suppressor in vast types of cancer." (PMID 30858761, 2019). "FOXD3 could act as a tumor suppressor to inhibit cell proliferation, migration and promote cell apoptosis in OC cells." (PMID 30858761, 2019). "Furthermore, compared with control group, FOXD3 overexpression group and 5-Aza-dC group showed obvious inhibition on tumor volume and tumor weight." (PMID 30858761, 2019). "Compared with normal tissues, the FOXD3 methylation level in tumor tissues was obviously increased." (PMID 30858761, 2019). "Finally, the effect of FOXD3 on tumor growth was investigated through in vivo xenograft experiments." (PMID 30858761, 2019). "Methylation of both tumor suppressors, FOXD3 and FOXF2, could be responsible for their down-regulation, thus disturbing their interaction with other proteins." (PMID 30987631, 2019). "Also, FOXD3 was reported to participate in the carcinogenesis of several cancers as a potential tumor suppressor." (PMID 27926503, 2017). "In addition, FOXD3 plays a critical role in tumor initiation and growth by interacting with other transcription factors like TWIST1." (PMID 28430585, 2017). "Moreover, the detailed mechanistic role of FOXD3 as a tumor suppressor in ATC needs to be ascertained." (PMID 28430585, 2017). "Furthermore, the FOXD3 tumor-suppressive cascade was downregulated in human cancers mainly due to DNA methylation." (PMID 26898989, 2016).
tumor (continued). "Collectively, these data suggest that FOXD3 may exert its tumor suppressing effects through different mechanisms in different types of malignancies." (PMID 26011451, 2015). "Many studies have demonstrated FOXD3 to be a tumor suppressor in various cancer cells." (PMID 26011451, 2015). "In addition, rescue experiments in FOXD3 over-expressed or silenced NB cells showed that restoration of NDRG1 expression prevented the tumor cells from FOXD3-mediated changes in these biological features." (PMID 24269992, 2013). "In summary, for the first time, we have demonstrated that FOXD3 is down-regulated in human NB, and FOXD3 exhibits tumor suppressor activity that affects the growth, invasion, metastasis, and angiogenesis of NB cells in vitro and in vivo through direct transcriptional regulation of NDRG1." (PMID 24269992, 2013). "This study extends our knowledge about the regulation of NDRG1 at the transcriptional level by tumor suppressive genes, and suggests that FOXD3 may be of potential values as a novel therapeutic target for NB." (PMID 24269992, 2013). "Immunohistochemical staining revealed that FOXD3 was expressed in the nuclei of tumor cells." (PMID 24269992, 2013). "In addition, we found that ectopic expression of FOXD3 inhibited the growth, migration, invasion, and angiogenesis of NB cells, suggesting the tumor suppressive roles of FOXD3 during the progression of NB." (PMID 24269992, 2013). "Furthermore, tumor cell-specific expression of VISTA, regulated by the forkhead box D3 (FOXD3) factor, promotes tumorigenesis and enhances PD-L1 expression on tumor-infiltrating macrophages in vivo, which is associated with increased intra-tumoral T regulatory cells." (PMID 37569880, 2023). "The FOXD3 gene knockdown could promote tumor cell proliferation." (PMID 37151068, 2023). "Furthermore, tumor cell-specific expression of VISTA, which is regulated by factor forkhead box D3 (FOXD3), promotes tumor onset and enhances PD-L1 expression on tumor-infiltrating macrophages in vivo and is associated with increased intra-tumoral T regulatory cells." (PMID 32600443, 2020). "Therefore, restored expression of FOXD3 also inhibits tumor growth in vivo." (PMID 30858761, 2019). "Next, we found that the reversed expression of FOXD3 in OC could suppress tumor growth." (PMID 30858761, 2019). "Our results suggested that FOXD3 could affect tumor growth and aggressiveness in OC." (PMID 30858761, 2019). "In comparison to the saline-treated animal group, SFN-pre-treated animals showed reduced gene expression of CSC markers, including Nanog, forkhead box D3 (FOXD3), Wnt3, ALDH1A1, and Notch4 during primary tumor growth." (PMID 37190316, 2023). "In the mouse xenograft model, SOX10 knockdown also blocked FOXD3/ERBB3 induction by Vemurafenib, reduced tumor growth and further enhanced the tumor-inhibiting capacity of Vemurafenib." (PMID 29295999, 2018). "FOXD3 expression was detected in all but one of the normal tissue samples, and in three BRAF wildtype tumor samples." (PMID 23324568, 2013). "For a subset of nine tumor-normal pairs, the expression of FOXB2, FOXD3, and FOXF1 was determined using real-time reverse-transcription PCR (RT-qPCR)." (PMID 23324568, 2013). "Next, we compared the tumor/normal expression ratios with the methylation measured by BSA (FOXB2 and FOXF1) or array (FOXD3)." (PMID 23324568, 2013). "Stable transfection of FOXD3 into SH-SY5Y cells resulted in decreased growth and tumor weight of subcutaneous xenograft tumors in athymic nude mice, when compared to those stably transfected with empty vector (mock)." (PMID 24269992, 2013). "Importantly, restoration of NDRG1 expression rescued the NB cells from FOXD3-mediated suppressive phenotypes in growth, aggressiveness and angiogenesis, suggesting that FOXD3 may exert its tumor suppressive function, at least in part, through transcriptional regulation of NDRG1 in NB." (PMID 24269992, 2013).
tumor (continued). "In addition, among the enriched TFs in NN-HF, we further identified NFκB-P65, FOXA3, FOXD3, SIX1, CDX2, and MEF2C which have been found to impact tumor progression." (PMID 38720110, 2024). "The research also indicated that after 36 days of therapy, the tumours’ transcriptomes showed downregulation of stem-cell-related genes such as aldehyde dehydrogenase 1A1 (ALDH1A1), NANOG, GDF3, and the embryonic pluripotency-maintaining transcription factor Forkhead box D3 (FOXD3)." (PMID 36295538, 2022). "With regard to its tumor suppressor role, it is not surprising that FOXD3 expression level may predict the prognosis of cancer patients." (PMID 26011451, 2015).
cancer (22 papers, 2013 to 2025). A tumor composed of atypical neoplastic, often pleomorphic cells that invade other tissues. "A decreased expression of FOXD3 was also associated with poor prognosis in high-grade gliomas25and its silencing increased cancer cell proliferation in colon cancer." (PMID 40610562, 2025). "It was reported that Forkhead box D3 (FOXD3) transcription factor is associated with several cancers." (PMID 28430585, 2017). "Recently, FOXD3 was found to be associated with cancer development." (PMID 27926503, 2017). "Furthermore, increased FOXD3 expression in cancer cell lines caused reduced proliferation rates, enhanced apoptosis, and reduced cell line invasiveness." (PMID 24133496, 2013). "Although previous studies have indicated that deregulation of certain FOX genes participates in the carcinogenesis, the functions and underlying mechanisms of FOXD3 in cancer still remain largely unknown." (PMID 24269992, 2013). "FOXD3 is located on human chromosome 1p31 and often acts as a transcriptional suppressor of tumorigenesis in numerous cancer types, including nasopharyngeal carcinoma, lung cancer, and ovarian cancer." (PMID 39494294, 2024). "FOXD3 as an epigenetic regulator mediates the transcriptional repression of multiple cancer genes including SLC25A26 and NANOG." (PMID 36966276, 2023). "In human cancer tissue, FOXD3 expression was reduced while EGFR/Ras/Raf/MEK/ERK signal pathway was activated." (PMID 27926503, 2017). "A previous study showed that FOXD3 expression decreased cancer cell migration that was efficiently reversed by TWIST1 overexpression." (PMID 28430585, 2017). "The genes that were shared by three different cancers (i.e., FGFR3, EPAS1, SRC, and FOXD3) are shown in coral, and the genes that were shared by two types of cancers (i.e., PPARG, FOXO1, CDK4, NKX3-1, PIK3R1, PRKCB and EDNRB) are shown in light pink." (PMID 28178311, 2017). "Although the EGFR-Ras-Raf-MEK-ERK signaling network has been identified as a novel target-based approach for cancer treatment, it is still unclear if the signal pathway is related with FOXD3." (PMID 27926503, 2017). "In human cancer tissue, the expression of FOXD3 was reduced, however, the EGFR/Ras/Raf/MEK/ERK pathway was activated." (PMID 27926503, 2017). "FOXD3 contributed to leukemogenesis, cancer cell proliferation and poor patient’s prognosis." (PMID 40610562, 2025). "Recent studies have reported the roles of FOXD3 in the development of cancer." (PMID 26011451, 2015). "The FOXD3 promoter was found to be hypermethylated in both screens and progressively hypermethylated in more advanced lesions with the highest methylation level in human cancer cases." (PMID 24133496, 2013). "Thus, we postulate that FOXD3 is a repressor of cancer metastasis." (PMID 28430585, 2017). "Aspirin dramatically increased FOXD3 concentrations in the nuclei of cancer cells and effectively promoted FOXD3 interaction with OLA1P2 promoter regions, providing convincing evidence that FOXD3 is a new aspirin target that could function in the control of lncRNA transcription." (PMID 26898989, 2016). "The causes of FOXD3 downregulation in cancer cells is still not clear." (PMID 26011451, 2015). "Upregulated FOXD3 protein levels and downregulated phosphorylated STAT3 (Tyr705) protein levels were identified by immunoblot analysis in nuclear extracts of clinical cancer samples obtained from patients who regularly used aspirin." (PMID 26898989, 2016). "We found a significant inverse correlation between FOXD3 protein levels and phosphorylated STAT3 (Tyr705) protein levels in nuclear extracts of clinical cancer samples obtained from patients who regularly used aspirin." (PMID 26898989, 2016). "The transcription factor forkhead box D3 (FOXD3) plays important roles in the development of neural crest and has been shown to suppress the development of various cancers." (PMID 26011451, 2015).
cancer (continued). "Forkhead box D3 (FOXD3) is a member of the forkhead box transcription factor family and often functions as a transcriptional repressor in the tumorigenesis of several types of cancers." (PMID 36627652, 2023). "FOXJ1 and FOXD3 were the members of forkhead box (FOX) and genes in FOX family played key roles in many cancer-related biological processes, such as metastasis, development, organization differentiation, cell proliferation, cell apoptosis, cell migration, invasion, and longevity." (PMID 28881636, 2017).
infection (2 papers, 2010 to 2022). The state of being infected such as from the introduction of a foreign agent such as serum, vaccine, antigenic substance or organism. "Infection of the human melanocyte line Hermes 3A with shATF2 effectively inhibited ATF2 expression, upregulated Mitf transcription and increased transcription of SOX10 and FOXD3 (from 7- to 10-fold) and to a lesser extent of Pax3 and Brn2 (from 1.5- to 2-fold)." (PMID 21203491, 2010).
kidney disease (1 paper, 2020). "However, whether FOXD3/FOXD4 related to kidney disease remains unclear and needs further investigation." (PMID 33274190, 2020).
FOXD3 also shares sentences with these, for which no sentence is quoted: non-small cell lung carcinoma (3 papers); Anophthalmia (2); coloboma (2); memory impairment (2); Addison's disease (1); Allergy (1); autoimmune polyglandular syndrome (1); chronic lymphocytic leukemia (1); chronic myeloid leukemia (1); Cirrhosis (1); congenital cataracts (1); endometrial cancer (1); endometrial tumors (1); ganglioneuroblastoma (1); ganglioneuroma (1); glioblastoma (1); Graves disease (1); liver cancer (1); MODY (1); nervous system tumors (1); neuroblastic tumor (1); Parkinson’s (1); Peters anomaly (1); retinal tumor (1); schizophrenia (1); schwannoma (1); seminoma (1); spinal cord ischemia (1); T-cell leukemia (1); teratocarcinoma (1).
A further 1 disease shares a sentence with FOXD3 in 1 paper.